HTT (huntingtin)
Diseases named in the same sentence as HTT in open-access papers (continued):
Sharing a sentence is not in itself a finding about the gene and the disease.
Parkinson disease (continued). "Together theseadvances make it clear that FUS is a key aggregated protein in ALS, just asα-synuclein is in Parkinson's disease and huntingtin is inHuntington's disease." (PMID 21541367, 2011). "Neither the HTT gene nor the ATXN2 gene showed a significant predictive effect on cancer risk in patients with Parkinson’s disease." (PMID 39974178, 2025). "We described an association of HTT, ATXN1 and ATXN2 with the risk of Parkinson’s disease, which reinforce the hypothesis of the common pathway of neurodegeneration." (PMID 39974178, 2025). "Axonal transport disruption and synaptic dysfunction are also features of each illness, although they are caused by diverse molecular mechanisms: tau in Alzheimer’s, α-synuclein in Parkinson’s, huntingtin in Huntington’s, and inflammation in multiple sclerosis." (PMID 40283923, 2025). "CPNQ targets huntingtin and α-synuclein to lower their pathological effects in cellular models of Huntington’s and Parkinson’s diseases, respectively, and we show here that this compound significantly inhibited only RyR1 (with an inhibitory trend on RyR2) at low [Ca2+]." (PMID 34793835, 2022). "Examples include the protection of paroxetine against dyskinesia in Huntingtin mutant mice and nigrostriatal neurodegeneration in Parkinson’s disease mouse model and the venlafaxine-mediated improvement of cognitive impairment and depressive behavior in multiple sclerosis mouse model." (PMID 33602262, 2021). "Misfolding and aggregation of proteins and peptides into amyloidogenic fibrils are hallmarks of a wide range of neurodegenerative disorders, including α-synuclein (αS) in Parkinson’s disease, the Aβ-peptide in Alzheimer’s disease, and Huntingtin (HTT) in Huntington’s disease." (PMID 34650037, 2021). "In addition, overexpression of TFEB has been reported to be beneficial in numerous disease models via clearance of aggregated protein (e.g., tau in Alzheimer's, α-syn in Parkinson's, and HTT in Huntington's)." (PMID 33224433, 2020). "Indeed, this is a primary characteristic of neurodegenerative diseases (e.g., α-syn in Parkinson's, tau in Alzheimer's, and HTT in Huntington's)." (PMID 33224433, 2020). "Verapamil enhanced the clearance of Parkinson’s disease-causing A53T mutant α-synuclein in cell lines and reduced the percentages of cells with aggregates of mutant huntingtin exon 1 in autophagy-competent but not in autophagy-null cells." (PMID 31000720, 2019). "For instance Alzheimer’s disease (AD) might be treated by removing beta-amyloid and phospho-Tau, Parkinson’s disease (PD) and Lewy Bodies disease might be treated by removing alpha-synuclein, Huntington’s disease (HD) by removing huntingtin protein and so on." (PMID 28413734, 2017). "Interestingly, tumor necrosis factor receptor-associated factor 6 (TRAF6)-mediated K27-linked ubiquitination has been shown to modify proteins such as α-synuclein and DJ-1 in Parkinson’s disease and huntingtin in Huntington’s disease, suggesting a role in neurodegenerative diseases." (PMID 40307574, 2025). "The concept that mutant huntingtin (mHtt) might spread from cell to cell in a prion-like fashion has gained substantial traction over the past decade, drawing parallels to what has been observed in diseases like Alzheimer’s, Parkinson’s, and ALS." (PMID 40943085, 2025). "htt (huntingtin), the Drosophila ortholog of the huntingtin gene (HTT) in humans, has been used as a model in the study of Huntington’s and Parkinson’s disease and is important for maintaining mobility in adult flies." (PMID 35052483, 2022). "Seven out of 18 genes are associated with neurological diseases: Alzheimer’s disease (CPT1A, SUFU, ZSWIM8, PDCD4), schizophrenia (HTT, NBEAL2) and Parkinson disease (PRDM13)." (PMID 32599769, 2020). "Additionally, PAR activity increases when it interacts with mutant huntingtin (HTT), linking it to other conditions like Alzheimer’s, Parkinson’s, and cerebellar ataxia." (PMID 41385186, 2025).
Parkinson disease (continued). "A case–control or cancer–non-cancer Parkinson’s disease comparisons were conducted to examine the size of the HTT, ATXN1 and ATXN2 CAG repeats in the different groups." (PMID 39974178, 2025). "Interestingly, there were seven genes associated with neurological disorders, including Alzheimer’s disease (CPT1A, SUFU, ZSWIM8, PDCD4), schizophrenia (HTT, NBEAL2) and Parkinson’s disease (PRDM13)." (PMID 32599769, 2020). "First, we noticed that several well characterized causal genes for AD (APP, PSEN2 and SORL1), HD (HTT and SLC2A3), and Parkinson's disease (PD) (PARK2, PARK7) were bound by REST in hESCs but not mESCs." (PMID 25990720, 2015).
Alzheimer disease (110 papers, 2009 to 2026). A progressive, neurodegenerative disease characterized by loss of function and death of nerve cells in several areas of the brain leading to loss of cognitive function such as memory and language. "Early synaptic dysfunction and progressive accumulation of pathogenic protein aggregates (e.g., huntingtin inclusions, amyloid plaques, and neurofibrillary tangles) lead to gradual, inescapable cognitive impairment and neuronal death in HD and Alzheimer’s disease (AD)." (PMID 29523177, 2018). "In this context, it is possible to speculate that Igf-1r levels might influence huntingtin oligomerization and/or aggregation kinetics, as previously proposed for the Alzheimer’s disease-linked human peptide, Abeta." (PMID 25140802, 2014). "Primarily, we found several aging (klotho, major vault 1, gelsolin, huntingtin, and fragile X mental retardation protein) and Alzheimer’s disease (ADAM10, apoE receptor, ChAT, APP, and PSEN1; most of these are also involved in aging) related sequences." (PMID 32449011, 2020). "In a mouse model of Alzheimer’s disease, 12 weeks of caloric restriction reduces Aβ plaque burden, and mice expressing human mutant huntingtin maintained on an alternate-day-feeding diet have reduced brain atrophy and decreased huntingtin aggregate formation." (PMID 31246952, 2019). "Aggregation‐prone proteins such as the huntingtin protein in Huntington's disease, α‐synuclein in Parkinson's disease, or mutant AD proteins in Alzheimer's disease abnormally interact with Drp1, leading to increased activity of Drp1, access of mitochondrial fragmentation and damage in neurons." (PMID 38760979, 2024). "They include prion protein involved in spongiform transmissible encephalopathies, amyloid beta-peptides in Alzheimer’s disease, tau tangles in Alzheimer’s disease, α-synuclein in Parkinson’s disease, huntingtin in Huntington’s disease, and islet amyloid polypeptide in type II diabetes." (PMID 39684527, 2024). "However, excessive autophagy can contribute to neurodegeneration, as in the case of Huntington’s and Alzheimer’s diseases, by altering the processing of mutant forms of Huntingtin and Amyloid β-protein precursor, respectively." (PMID 35892559, 2022). "These include tau in tauopathies, α-synuclein in synucleinopathies, such as Parkinson’s disease (PD), TDP-43 in frontotemporal dementia (FTD) and amyotrophic lateral sclerosis (ALS), huntingtin in Hungtinton’s disease (HD) and amyloid beta (Aβ) in Alzheimer’s disease (AD)." (PMID 35573838, 2022). "An impairment in the glymphatic clearance function has been shown to accelerate the accumulation of abluminal protein deposits, α-synuclein, Aβ and tau, and huntingtin, which, respectively, underpin small vessel disease, Parkinson's disease, Alzheimer's disease (AD), and Huntington's disease." (PMID 35359662, 2022). "Additionally, the localization of HTT in reactive astrocytes was demonstrated for the first time in a transgenic Alzheimer’s disease animal model." (PMID 31109380, 2019). "The neurodegenerative diseases, Alzheimer’s disease (AD), Parkinson’s disease (PD) and Huntington’s disease (HD), are characterized by aggregation of specific proteins, namely tau, α-synuclein, and mutant huntingtin with expanded polyglutamine (mHtt), respectively." (PMID 37500624, 2023). "In addition to Car8, ITPR1 function is impacted by a family of regulatory proteins including presenilin, huntingtin, DANGER, 80K-H, and cytochrome C. Mutations in two presenilin genes (PS1, PS2) account for the majority of familial early-onset Alzheimer's disease." (PMID 25734498, 2015). "This is true for HTT, the β-amyloid precursor protein (APP) and presenilins, responsible for early onset Alzheimer's disease (AD)." (PMID 22489754, 2012).
amyotrophic lateral sclerosis (79 papers, 2013 to 2025). Amyotrophic lateral sclerosis (ALS) is a neurodegenerative disease characterized by progressive muscular paralysis reflecting degeneration of motor neurons in the primary motor cortex, corticospinal tracts, brainstem and spinal cord. "Calpain-2 is shown to be involved in the breakdown of α-syn in PD and huntingtin protein in Huntington’s disease (HD), and it cleaves TDP43 proteins implicated in motor neuron function in Amyotrophic Lateral Sclerosis (ALS)." (PMID 38791036, 2024). "A number of human neurodegenerative disorders, including AD, Huntingtin’s, and Amyotrophic Lateral Sclerosis, show protein aggregation and accumulation." (PMID 31672849, 2020). "Notable examples are HD, caused by an expansion in the huntingtin gene (HTT), and certain familial forms of amyotrophic lateral sclerosis (ALS) that are considered monogenic, associated with mutations in SOD1 (superoxide dismutase), TARDBP (Transactive response DNA-binding protein), or FUS." (PMID 39857412, 2025). "Repeat expansion analyses were performed for 414 amyotrophic lateral sclerosis patients and 713 neurologically normal controls; pathogenic and intermediate-length repeat expansions in AR, ATXN2 and HTT were observed in 3.1% of the amyotrophic lateral sclerosis patients." (PMID 38585669, 2024). "Recently, it has been proposed that this mechanism also characterizes Amyloid-β (Aβ), tau, α-synuclein, SOD1, TDP-43, and huntingtin, involved in AD, PD, amyotrophic lateral sclerosis (ALS), frontotemporal lobar degeneration, and Huntington’s disease, respectively." (PMID 35416570, 2022). "One of the aims of our study was todetermine whether GAPDH and tTG can not only participate in the aggregation ofmutant huntingtin, but also contribute to the pathogenesis of a completelydifferent disease, amyotrophic lateral sclerosis (ALS)." (PMID 23819039, 2013). "For instance, they are involved in amyotrophic lateral sclerosis (ALS) by regulating motor neuron survival and they control Huntingtin protein accumulation in Huntington’s disease." (PMID 32878220, 2020). "Using an exome sequencing approach with ExpansionHunter, we investigated a Norwegian amyotrophic lateral sclerosis cohort for repeat expansions in AR, ATXN1, ATXN2 and HTT." (PMID 38585669, 2024). "Tominersen is an ASO targeting the huntingtin mRNA of Huntington’s disease (HD), and tofersen is an ASO targeting the superoxide dismutase 1 (SOD1) mRNA of SOD1 dependent amyotrophic lateral sclerosis (ALS)." (PMID 35745855, 2022). "For example, amyloid-like forms of Aβ and Tau, α-synuclein, huntingtin, FUS/TLS, TDP-43 or SOD1 are linked respectively to Alzheimer's (AD), Parkinson's (PD), Huntington's (Htt) and Amyotrophic Lateral Sclerosis (ALS) diseases." (PMID 25568955, 2015). "Prominently, toxic protein aggregation such as those formed by β-amyloid peptide (Aβ) and tau proteins in Alzheimer’s disease, TDP-43/FUS in amyotrophic lateral sclerosis (ALS), and huntingtin protein in Huntington’s disease have been studied as archetypical phase separation processes." (PMID 33168632, 2021). "For example, such conformational changes have been seen for: Aβ, associated with Alzheimer’s disease; α-synuclein with Parkinson’s disease; TDP-43, FUS and others with amyotrophic lateral sclerosis (ALS) and frontotemporal dementia (FTD); and huntingtin with Huntington’s disease." (PMID 31390360, 2019). "Norwegian amyotrophic lateral sclerosis patients (n = 414) and neurologically healthy controls adjusted for age and gender (n = 713) were investigated for repeat expansions in AR, ATXN1, ATXN2 and HTT using short read exome sequencing and the ExpansionHunter software." (PMID 38585669, 2024).
amyotrophic lateral sclerosis (continued). "The pathogenic proteins most commonly implicated in the accumulation of “misfolded” brain aggregates include, among the others, tau and β-amyloid in AD, α-synuclein in PD, huntingtin in HD and FUS, ZNF and TDP-43 in amyotrophic lateral sclerosis (ALS) and Fronto-Temporal Dementia (FTDs)." (PMID 38993838, 2024). "Most neurodegenerative diseases are characterized by intracellular or extracellular aggregation of misfolded proteins, such as Aβ and tau in AD, α-synuclein in PD, huntingtin in HD and transactive response DNA-binding protein-43 (TDP-43) in amyotrophic lateral sclerosis (ALS)." (PMID 35955427, 2022).
cognitive decline (35 papers, 2013 to 2026). "HD, a neurodegenerative disorder characterized by progressive motor dysfunction, cognitive decline, and psychiatric symptoms, is caused by mutations in the HTT gene, which encodes the Huntingtin protein (HTT)." (PMID 40469903, 2025). "An expansion of 40 or more CAG repeats produces pathogenic forms of the HTT protein (mutant HTT, mHTT), which induces a cascade of molecular pathologies that leads to behavioral changes, cognitive decline and choreic movements." (PMID 36547263, 2023). "HD is an autosomal dominant neurodegenerative disease characterized by progressive motor, behavioral and cognitive decline which caused by a pathogenic repeat expansion of the cytosine-adenine-guanine trinucleotide in exon 1 of the HTT gene on chromosome 4." (PMID 34922574, 2021). "Also, HD, a well-known incurable hereditary neurodegenerative condition, causes motor impairment and cognitive decline because of the mutated and toxic huntingtin (HTT) protein function." (PMID 35842587, 2022). "Huntingtin and its pathological variants are widely expressed, but the central nervous system is mainly affected, as proved by the wide spectrum of neurological symptoms, including behavioral anomalies, cognitive decline and motor disorders." (PMID 33167595, 2020). "HD is a progressive neurodegenerative disorder caused by a genetic mutation involving the huntingtin gene (HTT), characterized by motor dysfunction, cognitive decline, and psychiatric symptoms." (PMID 39944166, 2025). "HD is characterised by the development of progressive motor impairment, cognitive decline and behavioural problems, caused by an expanded trinucleotide CAG sequence in the Huntingtin (HTT) gene –." (PMID 30334742, 2018). "In vivo, A36 displayed favorable pharmacokinetics and central nervous system exposure; treatment reduced striatal neurodegeneration, mutant huntingtin aggregation, and motor deficits in HD R6/2 mice, and lowered phosphorylated tau, neuroinflammation, and cognitive decline in tauopathy PS19 mice." (PMID 41894510, 2026). "Two patients had a mutation detected in clinic outside the gene panel; a deletion in SPG4 in a patient with cognitive decline, slowly progressive muscle weakness and spasticity, and a 44 CAG-repeat in the Huntington (HTT) gene (>40 repeats is pathogenic) in a patient with dementia and subtle chorea." (PMID 39869842, 2025). "HD is an NDD caused by mutations in the huntingtin (HTT) gene that cause abnormal expansion of CAG repeats, with clinical manifestations including chorealike involuntary movements, neuropsychological symptoms, and progressive cognitive decline." (PMID 39716330, 2024). "HD is an autosomal-dominant, progressive neurodegenerative disease with the clinical symptoms of chorea and dystonia, incoordination, cognitive decline, and behavioral abnormal which is characterized by the presence of the aggregated mutant huntingtin (mHTT) protein." (PMID 34922574, 2021). "Our finding that inhibiting Akt-mediated HTT phosphorylation reduces APP presynaptic levels in APPPS1 mice suggests that increased Akt activity might contribute to higher presynaptic APP levels in AD brains, leading to synapse loss and cognitive decline." (PMID 32452382, 2020). "In this case, we concluded that the PolyQ tract on huntingtin function also depends on the stage of the pathology underlying the cognitive decline, with a positive effect in patients that still have normal cognitive performances and a negative effect when the cognitive decline appears." (PMID 40844528, 2025). "HD is an autosomal dominant neurodegenerative disorder that leads to progressive motor dysfunction, cognitive decline, and psychiatric disturbances, primarily due to the expansion of CAG repeats in the HTT gene, resulting in mutant huntingtin protein aggregation." (PMID 40603982, 2025).